TNF (tumor necrosis factor)
Diseases named in the same sentence as TNF in open-access papers (continued):
Sharing a sentence is not in itself a finding about the gene and the disease.
periodontitis (continued). "Periodontitis is one of the main causes of tooth loss and is able to increase the plasma concentrations of proinflammatory mediators such as IL-1, IL-6, and TNF-α, thereby contributing to worsening neuroinflammatory processes in the brain and ultimately resulting in cognitive impairment." (PMID 33514062, 2021). "Periodontitis is the cause of a systemic inflammatory process mediated by C-reactive protein, interleukin 1b (IL-1b), interleukin 6 (IL-6), and tumor necrosis factor alpha (TNF-α), among others." (PMID 33961166, 2021). "Although not yet described in cleft pathology, an increased oral mucosal level of TNF-α has been outlined in a variety of chronic oral inflammatory conditions, most notably in periodontitis, in which TNF-α has been linked to ongoing soft and hard tissue destruction." (PMID 34199238, 2021). "Etanercept is effective in preventing mandibular bone loss in FcγRIIb-/- mice, suggesting that anti-TNF-α therapy may be able to ameliorate mandibular bone loss in SLE patients with periodontitis." (PMID 33861790, 2021). "Genetic variations of IL-1β + 3954 appear to be associated with increased risk of periodontitis in Koreans (Detection of association between periodontitis and polymorphisms of IL-1beta + 3954 and TNF-alpha −863 in the Korean population after controlling for confounding risk factors)." (PMID 33916672, 2021). "Anti-TNF-α will be a potential way to prevent periodontitis risk." (PMID 35046930, 2021). "TNF-α-induced inflammation may contribute to severe periodontitis leading to alveolar bone loss in SLE patients." (PMID 33861790, 2021). "In our study, the expression of inflammatory cytokines in OSCC showed that periodontitis-associated bacteria significantly (p < 0.05) upregulated IL-6, TNF-α, IL-18, ASC (up to six times), and caspase-1 (up to four times) but downregulated NF-κB, NLRP3, and IL-1β (less than 0.5 times)." (PMID 34660289, 2021). "Therefore, there is a need to carry out this updated meta-analysis to summarize the latest relationship between TNF-α gene polymorphism and periodontitis susceptibility." (PMID 32899013, 2020). "The link between osteoporosis and periodontitis is probably represented by inflammatory cytokines, such as interleukin-1, -6 and tumor necrosis factor alpha, responsible for bone loss in osteoporosis due to their effects on osteoclast activity and destruction of tooth-supporting tissues." (PMID 32260243, 2020). "TNF is known to play a key role in driving chronic inflammation as well as in pathological bone erosion associated with multiple inflammatory bone diseases, such as RA, periodontitis and periprosthetic osteolysis." (PMID 33133025, 2020). "It is known that inflammatory cytokines for example, TNF and IL-1beta, play an important role in periodontitis, inducing bone loss by promoting the expression of receptor activator of nuclear factor kappa-B ligand (RANKL) in other cells such as T cells and fibroblasts, favoring osteoclastogenesis." (PMID 31921182, 2019). "The results of some studies revealed an association between TNF-α-308 SNP and periodontitis." (PMID 30755190, 2019). "Bacteremia caused by bacteria invades the blood stream through the periodontitis lesion and an influx of inflammation mediators, such as interleukin (IL)-6 and tumor necrosis factor (TNF)-α, produced in the lesion can be introduced into the systemic circulation." (PMID 31336777, 2019). "As a chronic inflammation disease, periodontitis is associated with dysfunction of MSCs, and the high levels of LPS and TNFα in the periodontal environment could influence the efficiency of MSCs-based tissue regeneration." (PMID 31440385, 2019). "Different mechanisms have been implicated in the increase in TNF-α and could contribute to the development of periodontitis." (PMID 29680852, 2018).
periodontitis (continued). "Periodontitis is a chronic inflammatory disease, and it is believed that periodontitis has the ability to induce local and host immune responses and to cause both transient bacteremia and the release of inflammatory mediators such as ILs and TNF-α." (PMID 29980169, 2018). "Association of SNPs in vascular endothelial growth factor (VEGF), IL-6, IL-10, IL-1beta, interferon alpha, TNF-alpha genes with immunoregulatory function revealed that C allele of VEGF, an allele of IL-10 and GG genotype of TNF-alpha, was individually associated with chronic periodontitis." (PMID 29489938, 2018). "In Aurer study on different groups including chronic periodontitis patients, healthy group, and patients with tooth loss showed that in addition to TNF-α, salivary levels of other inflammatory factors such as C3, CRP, and α-2M were lower in periodontitis group compared to other groups." (PMID 29238418, 2017). "Hence, considerable attention was paid in drawing an association between periodontitis and certain inflammatory cytokines, such as interleukin-1 (IL-1), tumor necrosis factor-α (TNF-α), and matrix metalloproteinase-8 (MMP-8)." (PMID 28662701, 2017). "The formation of AGEs may influence the collagen stability and vascular integrity and could also aggregate macrophage and monocyte receptors, thereby aggravating the susceptibility to periodontitis through the stimulation of IL-1 and TNF-α." (PMID 26339142, 2015). "Interleukin‐6 (IL‐6) and tumor necrosis factor‐alpha (TNF‐α) are pro‐inflammatory cytokines that regulate immune response and bone metabolism and have been suggested as one of the most potent cytokines that were associated with periodontitis and RA." (PMID 29744142, 2015). "The plasma level of TNF-α was also measured to assess whether trans-anethole treatment was associated with reduce inflammation in LPS-induced periodontitis." (PMID 25587321, 2014). "However, the present study managed to showed an association of TNF-α GG genotype (OR = 3.716; 95% CI = 1.943 - 7.104) with periodontitis." (PMID 23046796, 2012). "Furthermore, blockade of the activity of TNF-α was found to inhibit the inflammatory response and bone loss in a primate model of experimental periodontitis." (PMID 20607056, 2010). "CBD significantly reduced bone loss in the experimental periodontitis model, downregulated TNF-α, and reduced TLR4 expression in gingival tissues, suggesting that CBD, particularly in topical form, could be an effective therapeutic agent for treating periodontitis." (PMID 40332414, 2025). "In addition, periodontitis causes the secretion of cytokines such as TNF-α, IL-1β, and IL-6, leading to systemic inflammation, which may connect periodontal disease to a number of systemic problems, such as cardiovascular and neurological conditions." (PMID 40243684, 2025). "Similarly, the plausible mechanisms explaining the association between low salivary flow rate and periodontitis might be due to also the increased proinflammatory cytokine levels, such as IL-2, IL-17, and TNF, triggering glandular damage and hyposalivation." (PMID 37408223, 2023). "It has been demonstrated that human PDL cells exposed to P. gingivalis may produce fewer pro-inflammatory cytokines when treated with the phenolic acid resveratrol, which was found to decrease IL-1β, IL-6, IL-8, and TNF-α levels as well as alveolar bone loss in an animal model of periodontitis." (PMID 37317243, 2023). "Gram-negative anaerobic bacteria, especially Porphyromonas gingivalis, are the main pathogenic bacteria of periodontitis, and their main pathogenic component, lipopolysaccharide, can induce bone destruction by triggering the release of proinflammatory mediators such as IL-6 and TNF-α." (PMID 35586136, 2022).
periodontitis (continued). "TNF-α promotes the increase of osteoclast progenitor cells in vivo, and inhibition of human osteoclastogenesis in vitro by EA has also been reported; therefore, we suggested that EA could inhibit alveolar bone destruction associated with periodontitis." (PMID 36794024, 2022). "The present meta-analysis showed that the polymorphisms of the members IL-2 and TNF-α of Th1 cytokine family may be associated with the pathogenesis of periodontitis or the prevention of periodontitis risk, while the polymorphism of IFN-γ is not related to periodontitis risk." (PMID 35046930, 2021). "For example, it has been reported that tissue affected by periodontitis and normal periodontal tissue show differences in the methylation status of promoters for inflammation-related genes such as those encoding interleukin (IL)-8, tumor necrosis factor-alpha (TNFα) and toll-like receptor-2 (TLR2)." (PMID 33671221, 2021). "Therefore, the aim of the present study was to investigate the effect of F. alocis and additionally of the pro-inflammatory cytokine tumor necrosis factor-alpha (TNFα) on visfatin and other pro-inflammatory and proteolytic molecules associated with periodontitis in human macrophages." (PMID 33513808, 2021). "Consequently, active periodontitis is associated with elevated salivary concentrations of pro-inflammatory mediators, including interleukin-1 beta (IL-1β), interleukin-6 (IL-6), interleukin-8 (IL-8), and tumor necrosis factor alpha (TNF-α)." (PMID 35048079, 2021). "Statins majorly affected Th1, Th2 and Th17-related cytokines in the periodontitis group, possibly being ascribed to LPS-activated mononuclear macrophages under the pathological state of periodontal infection and subsequent inflammatory response caused by the produced IL-1, IL-6 and TNF-α." (PMID 33417619, 2021). "Therefore, we speculated that there may be ethnic differences in the correlation between the TNF-α-308G/A gene polymorphism and the susceptibility to periodontitis." (PMID 32899013, 2020). "Therefore, the TNF-α gene polymorphisms play a pivotal role in periodontitis susceptibility." (PMID 29449347, 2018). "Therefore, it is reasonable to consider that the increased M1 polarization of macrophages during chronic periodontitis can be also a risk factor for AD, because the elevated levels of TNF-α and IL1-β are associated not only with the cognitive decline but also with the progression of AD." (PMID 24363500, 2013). "Another common pathogenic link affecting periodontitis and RA is the monocytic hypersecretory state, which may induce the secretion of excessive pro-inflammatory cytokine secretion, such as IL-1b, TNF-a and IL-6, which results in the stimulation of degrading enzymes and tissue destruction." (PMID 22035090, 2011). "We specifically observed a reduction in TNF‐α levels in SHED cells stimulated with LPS, a pro‐inflammatory cytokine predominantly released by macrophages and critically involved in periodontitis‐associated bone loss." (PMID 40955713, 2026). "The expression trends of CFI (upregulated) and COQ2 (downregulated) were first confirmed in TNF-α/IL-1β-stimulated human periodontal ligament cells and further validated in a rat ligature-induced periodontitis model." (PMID 41998822, 2026). "Biologic therapies targeting cytokines downstream of NF-κB activation have shown efficacy in treating inflammatory bone diseases, including periodontitis.TNF-α inhibitors, such as adalimumab and infliximab, are widely used in inflammatory conditions." (PMID 41484074, 2026). "TNF-α levels have been reported to be increased in the gingival crevicular fluid in patients with periodontitis and during orthodontic tooth movement." (PMID 40360766, 2026). ", significantly attenuates key pro-inflammatory cytokines (IL-6, IL-1β, and TNF-α) at both the mRNA and protein levels in a rat periodontitis model." (PMID 41484074, 2026).
periodontitis (continued). "Periodontitis elevates circulating pro-inflammatory cytokines (e.g. TNF-α, IL-1β, IL-6), which can cross the blood–brain barrier, activate microglia and promote neuroinflammation—a process implicated in amyloid-beta accumulation and tau pathology." (PMID 41406907, 2026). "In periodontitis, TNF-α is a central factor mediating periodontal tissue destruction, which promotes osteoclast differentiation and leads to alveolar bone resorption." (PMID 41592028, 2026). "confirm that MCP‐1 and TNF‐α levels are higher in sera from periodontitis patients than in healthy controls, differences of IL‐6 levels differed among studies." (PMID 41580300, 2026). "The results indicate that EVO exhibits potent antimicrobial activity against key periodontal pathogens and suppresses pathogen-induced ROS generation as well as the release of pro-inflammatory cytokines (IL-1β, IL-6, TNF-α) under periodontitis conditions." (PMID 42072113, 2026). "For instance, to use a genetic variant in the TNF gene region that encodes tumor necrosis factor-alpha (TNF-α), it would be necessary to assume that perturbation of circulating TNF-α can only affect the outcome via periodontitis." (PMID 40344437, 2025). "Repeatedly elevated inflammatory markers, including IL-6, TNF-α, and CRP, as well as regulatory T-cells, were observed in individuals with periodontitis, indicating a potentially shared pathogenic environment with certain tumors." (PMID 41384174, 2025). "In periodontitis, the immune system overreacts, producing too many inflammatory signals, such as interleukin-6 (IL-6), interleukin-1beta (IL-1β), and tumor necrosis factor-alpha (TNF-α)." (PMID 41333792, 2025). "TNF‐α and IL‐1β are pro‐inflammatory cytokines that are involved in the initiation and progression of periodontitis and have been used to establish models of inflammatory environments." (PMID 39572253, 2025). "As with reports of increased TNF-α and IL-1β levels in gingival tissue and serum from patients with periodontitis, the present study also showed higher levels of TNF-α and IL-1β in the L group." (PMID 39941567, 2025). "Compared to the Experimental Periodontitis (EP) group, both inhibitors significantly downregulated the mRNA expression of Il‐6, Tnf‐α, and Rankl, and also reduced TNF‐α protein levels in gingival tissues." (PMID 41041963, 2025). "ESM-1 levels were significantly related to TNF-α and VEGF-A, while VEGF-A and TNF-α values were also correlated in both the control and post-treatment periodontitis groups." (PMID 40426985, 2025). "Conversely, knockout of TNF-α has been reported to mitigate inflammation and alveolar bone destruction in periodontitis models." (PMID 41154468, 2025). "Tumor necrosis factor α (TNF-α), a major inflammatory factor, plays a dual role in both the inflammatory response of periodontitis and glycolipid metabolism." (PMID 41244040, 2025). "Beyond bacterial pathogens, the characteristic systemic low-grade inflammatory state of periodontitis elevates circulating levels of C-reactive protein, IL-6 and TNF-α, representing another crucial pathway linking periodontitis to NAFLD." (PMID 40951429, 2025). "Its anti-inflammatory properties help lower the levels of pro-inflammatory cytokines such as TNF-α, IL-1β, and IL-6, which are crucial in driving tissue damage in periodontitis." (PMID 40530190, 2025). "The concentrations of TMAO and TNF-α in saliva were higher in the periodontitis group compared to controls (respectively; p = 0.003 and p = 0.004), and this finding was statistically significant." (PMID 40131489, 2025). "Reduced pro-inflammatory cytokine responses, such as TNF-α, have been considered beneficial in periodontitis." (PMID 41157245, 2025). "Peripheral neutrophils from patients with periodontitis release increased amounts of IL-1β, IL-8, IL-6, and tumor necrosis factor (TNF)-α upon stimulation with periodontal pathogens." (PMID 40572711, 2025).
periodontitis (continued). "In the rat model of ligature-induced periodontitis, expression levels of the proinflammatory cytokines TNF-α, IL-1β, and IL-6 in gingival tissue were significantly reduced in the E1 and E2 groups compared with those in the PC group." (PMID 40808155, 2025). "In vivo studies showed a protective effect against P. gingivalis-induced periodontitis in rats by reducing bacterial load and regulating IL-1β and TNF-α production." (PMID 41567672, 2025). "Peptostreptococcus in periodontitis can stimulate various immune cells and produce TNF-α, IL-6, or IL-1β to trigger an inflammatory response, promoting bone resorption and causing irreversible destruction of the periodontium." (PMID 40387401, 2025). "In the current study, as periodontitis was induced, a significant increase in the production of pro-inflammatory cytokines TNF-α and IL-6 was observed." (PMID 40007939, 2025). "Within the limitations of this retrospective study, non-surgical periodontal therapy was associated with significant reductions in systemic inflammatory biomarkers (CRP, IL-1β, IL-6, TNF-α) across all stages and grades of periodontitis." (PMID 41440349, 2025). "According to the post hoc Bonferroni test results, the mean salivary and GCF levels of TNF-α and IL-1β in healthy individuals were significantly lower than those with periodontitis and gingivitis." (PMID 40265034, 2025). "In periodontitis, elevated levels of TNF-α in saliva and GCF closely correlate with the extent of tissue damage and the degree of host response." (PMID 41280962, 2025). "Consistently, increasing concentrations of chemokines such as TNFα, IL1β and CXCL8 in the gingival crevicular fluid and peri-implant crevicular fluid are associated with the severity of periodontitis and peri-implantitis." (PMID 40565042, 2025). "This led to the following research question: What is the effect of closed-field scaling and root planning on serum levels of IL-1β, IL-4, IL-6, IL-8, IL-10, IL-12p70, IL-17A, VEGF, and TNF-α in patients with periodontitis and high blood pressure?" (PMID 40002786, 2025). "In severe periodontitis, TNF-α levels differed significantly between groups, while IL-1β did not, with mean cytokine levels lower in the impaired group." (PMID 41149360, 2025). "In periodontitis, it can be also released by periodontal ligament fibroblasts, T and B cells under pro-inflammatory stimuli (e.g. TNF-α, IL-1β, and IL-6) in the presence of LPS." (PMID 40736688, 2025). "The ESM-1 values were shown to be significantly correlated with VEGF-A (p < 0.05), as well as TNF-α (p < 0.05), and the VEGF-A values correlated with the TNF-α values (p < 0.05), in both the control and post-therapy periodontitis groups." (PMID 40426985, 2025). "Macrophage polarization critically influences periodontitis progression: pro-inflammatory M1 macrophages exacerbate bone resorption through IL-6 and TNF-α secretion, whereas anti-inflammatory M2 macrophages facilitate tissue repair via cytokines such as IL-10." (PMID 41124423, 2025). "In periodontitis samples, pathway activity scores demonstrated a significant activation of inflammatory pathways (NF-κB, TNF and IL-17), with these signatures remaining high throughout the disease course." (PMID 40902506, 2025). "And periodontitis disease progression was inhibited by reducing M1 macrophage polarization and decreasing the iNOS, TNF-α, and IL-6 expression." (PMID 40032778, 2025). "Periodontitis is characterized by a persistent immune inflammatory response to bacterial biofilms, leading to systemic dissemination of cytokines such as tumor necrosis factor (TNF)-α, IL-1β, IL-6, and prostaglandins." (PMID 40941475, 2025). "These receptors are known to mediate anti-inflammatory responses by inhibiting the production of pro-inflammatory cytokines such as TNF-α, IL-6, and NF-κB, which are central to the pathogenesis of periodontitis." (PMID 40256760, 2025).